OCM2 (oncomodulin 2)
Synonyms: OCM; OM
Tractability: Antibody: the Human Protein Atlas places it where antibodies can reach.
Gene: Protein-coding gene on chromosome 7 (97,984,687 to 97,991,169, reverse strand). Ensembl gene ENSG00000135175.
Subcellular location (Human Protein Atlas): Plasma membrane; Cytosol
Gene Ontology:
Molecular function: calcium ion binding
Cellular component: cytoplasm
Genetic constraint (gnomAD): Loss-of-function variants: 6 observed, 12.6 expected, observed/expected ratio (o/e) 0.48, 90% interval 0.26 to 0.94. The upper end of that interval is the gene's LOEUF score, 0.94, which puts it in group 3 of 6, group 1 being the genes least tolerant of losing a copy. Missense variants: 118 observed, 136.07 expected, observed/expected ratio (o/e) 0.87, 90% interval 0.75 to 1.01. Synonymous variants: 40 observed, 50.2 expected, observed/expected ratio (o/e) 0.8, 90% interval 0.62 to 1.04.
Homologues: Orthologues: chimpanzee OCM2 (100% identical), dog OCM (99% identical), guinea pig Ocm (99% identical), macaque OCM (99% identical), rat Ocm (91% identical), mouse Ocm (90% identical), zebrafish pvalb5 (50% identical). Paralogues in human: OCM (98% identical), PVALB (51% identical).
Diseases named in the same sentence as OCM2 in open-access papers:
OCM2 is named in the same sentence as 1 disease in open-access papers, as found by Europe PMC text mining. Sharing a sentence is not in itself a finding about the gene and the disease. The quoted sentences say what the papers report.
cancer (1 paper, 2023). A tumor composed of atypical neoplastic, often pleomorphic cells that invade other tissues. "Indeed, high expression of OCM2 was demonstrated earlier in rat cancer cell lines undergoing neoplastic transformation." (PMID 37239828, 2023).